MALAT1 (metastasis associated lung adenocarcinoma transcript 1)
Diseases named in the same sentence as MALAT1 in open-access papers (continued):
Sharing a sentence is not in itself a finding about the gene and the disease.
tumor (continued). "In addition, the cytoplasmic localization and tumor-restricted overexpression of SNHG5 make it an attractive candidate for lncRNA-directed therapeutics, building on preclinical experience with antisense oligonucleotides against other oncogenic lncRNAs such as MALAT1." (PMID 41550840, 2026). "Furthermore, gma-miR159 from soybean inhibits TCF7, which may suppress breast cancer cell proliferation, while gma-miR4995, also from soybean, targets MALAT1 and NEAT1, two long non-coding RNAs involved in tumor progression, thereby exerting anti-tumor effects." (PMID 40565979, 2025). "Interestingly, in tumours predominantly expressing A3B, high NEAT1 or MALAT1 expression significantly correlated with reduced levels of the APOBEC-mediated mutation signatures, aligning with our hypothesis that NEAT1 and MALAT1 can regulate A3B activity by sequestration." (PMID 39322638, 2024). "Furthermore, MALAT1 stimulates mammarytumor growth: transfecting siMALAT1 into MDA-MB-231 and ZR-75-1 cell culturessuppressed the proliferation ability of cells, whereas subcutaneous injectionof transfected tumor cells to mice also reduced tumor growth rate and size." (PMID 37538803, 2023). "In addition to the two aforementioned axes (lncRNA-ATB/miR-200c/ZNF217/TGF-β2 and MALAT1/miR-141-3p/ZNF217/TGF-β2), both involved in the activation of the TGF-β signaling pathway and EMT, ZNF217 is part of additional intricate ceRNA-driven regulatory circuits involved in tumor progression." (PMID 36551531, 2022). "Moreover, in NSCLC tumor tissues and cell lines (A549, H1299, HCC827, and H358), SOX9 could activate MALAT1 expression by binding MALAT1 promoter on a specific site (5′-TCATTGTGT-3′), thus creating a positive feedback loop which dramatically increases MALAT1 downstream effects." (PMID 32438606, 2020). "Moreover, multiple molecular networks, and not MALAT-1 alone, contribute to tumor development." (PMID 32700729, 2020). "lncRNAs with a demonstrated ability to regulate tumor metastasis (e.g., lincIRX5 and lincFOXF1) and lncRNAs with unclear functions (e.g., lincMTX2 and lincTNS1) might have the potential to regulate CRC liver metastasis in a manner similar to that of TUG1 and MALAT1." (PMID 28628609, 2017). "However, our functional analysis revealed that though MALAT1 is less abundantly expressed in TNBC subtype compared to luminal subtypes, it plays crucial role in regulating the expression of key genes that are involved in tumor progression and metastasis in TNBC cells." (PMID 27250026, 2016). "Moreover, amplification of MALAT1 in tumor tissues may play an important role for its up-regulation, and it seems that the gene amplification in tumor tissues emerges during ESCC progression, but is not derived from germline origins." (PMID 25613496, 2015). "Our results also revealed a negative association between MALAT1 expression and ATM-CHK2 pathway phosphorylation in tumor tissues, suggesting that up-regulation of MALAT1 may promote ESCC growth by dephosphorylation of the ATM-CHK2 pathway, which may loose the cell cycle arrest." (PMID 25613496, 2015). "As for the case of miRNA expression, the expression of H19, MALAT1 and BCL2 did not correlate in a statistically significant way with smoking status or tumor stage." (PMID 35723379, 2022). "The analysis showed that the expression in both negative vs. both positive groups (coexpression) of MALAT1 and BACH1 was correlated with the size of tumor, metastasis in LN, and TNM stage (p ≤ 0.000, 0.000, and 0.001, respectively)." (PMID 35096427, 2022). "Here, we detected a modest correlation between expression levels of MALAT1 and VDR in tumor tissues but not in ANCTs." (PMID 32514489, 2020). "In a recent study, MALAT1 was found targeted by miR-200c, which plays a negative role in tumor growth and EMT; accordingly, an inverse correlation between MALAT1 and miR-200c levels emerged in EEC tissues." (PMID 29739426, 2018).
tumor (continued). "Moreover, some lncRNAs could regulate metastasis and/or irradiation-resistance in NPC, e.g., MALAT1, AFAP1-AS1, LINC01420, ROR and HNF1A-AS have been reported to promote the proliferation and metastasis of NPC cells, but LINC0086 is negatively related to the tumor size and metastasis of NPC." (PMID 29050268, 2017). "HOTAIR, MALAT1, HULC, and UCA1 were similarly expressed between tumor tissues and nontumor tissues in HCC patients (P = 0.448, 0.138, 0.085, and 0.373, resp)." (PMID 26136615, 2015). "Our results showed that MALAT1 was upregulated mostly in late-stage tumor tissues, indicating that it mainly functions in the advanced stages of ESCC but not tumor initialization." (PMID 25613496, 2015). "In our previous study, MALAT1 was unregulated in HCC and served as a negative prognostic factor for tumor progression and patient survival." (PMID 25624916, 2015). "Among them, MALAT1, H19 and HOTAIR were significantly higher in plasma of tumor patients, while the other 3 lncRNAs showed no significant changes." (PMID 26096073, 2015). "In this study, we identified a subset (8.3%) of CRC patients who, irrespective of tumor metastasis, have a poorer prognosis due to their tumor tissues exhibiting high TCF12 mRNA, high MALAT1, low β-catenin mRNA, and high cyclin D1 mRNA levels, referred to as the TMBC pattern." (PMID 39768127, 2024). "In our study, we discovered that 8.3% of CRC patients, regardless of whether they experience tumor metastasis, have poor prognosis due to their tumor tissues expressing high TCF12 mRNA, high MALAT1, low β-catenin mRNA, and high cyclin D1 mRNA." (PMID 39768127, 2024). "MALAT1 and miR-146a expressions in HCC tumor tissues were negatively correlated (P < 0.001)." (PMID 32435156, 2020). "More accurately, MALAT1 level in TNBC and HER2+ subtypes could be quantified to predict tumor recurrence and metastasis in lymph-node negative (LN-) patients." (PMID 27250026, 2016). "A comparison of expression in tumour tissue (TT) and non-malignant mucosa tissue (MT) showed significant upregulation of CCAT1 and linc-ROR in TT (p < 0.001 and p = 0.001, respectively) and downregulation of ANRIL, MIR155HG and MALAT1 (p = 0.001, p = 0.010, p = 0.001, respectively)." (PMID 30205577, 2018).
infection (35 papers, 2011 to 2025). The state of being infected such as from the introduction of a foreign agent such as serum, vaccine, antigenic substance or organism. "Next, to explore the functional role of Malat1/Maf/IL-10 pathway in vivo, we studied the role of Malat1 in infection models in which IL-10 deficiency either promotes pathogen clearance or enhances immunopathology." (PMID 32321759, 2020). "It isnoteworthy that the suppression of MALAT1 expression resulted in the mitigation of inflammatory damage through the inhibition ofneutrophil chemotaxis and the influx of immune cells to the infection site." (PMID 41393400, 2025). "This study focuses on characterize the expression profile of LincRNA-cox2, Lethe, lincRNA-EPS, Malat1 and Gas5 during infection of macrophages by B. abortus." (PMID 38464511, 2024). "The Malat1-KO or wild-type mice were infected with S. japonicum cercariae, and the liver tissues were collected at day 49 post-infection for qPCR, IHC and collagen deposition analyses." (PMID 39363237, 2024). "Given that antigen-specific miR-15/16Δ/Δ T cells exhibited enhanced memory cell differentiation during LM-GP33 infection, we further tested the role of Malat1:miR-15/16 interaction in this model using the P14 adoptive transfer system." (PMID 38127070, 2023). "Taken together, these data demonstrate that miR-15/16 restrict memory cell differentiation, and reveal the ability of Malat1:miR-15/16 interaction to enhance memory cell differentiation across infection contexts." (PMID 38127070, 2023). "Accordingly, Malat1 mutation diminished memory cell persistence following LCMV Armstrong and Listeria monocytogenes infection." (PMID 37547023, 2023). "MALAT1 has been shown to regulate T-cell function, predominantly in animal models of infection or immunopathology." (PMID 36869729, 2023). "We have also shown that the infection of epithelial cells by N. gonorrhoeae leads to significant overexpression of the long non-coding RNAs (lncRNAs), including MALAT1, ERICD, and RP11-510N19.5." (PMID 35456069, 2022). "In a mouse study, Malat1 knockouts in Th1 and Th2 cells resulted in lower the expression of the immunosuppressant IL-10 and more robust immune responses in infection." (PMID 34564316, 2021). "Knockdown of MALAT1 suppressed inflammation by lowering neutrophil chemotaxis and immune cell infiltration at the infection site." (PMID 34451848, 2021). "We first examined the knockdown efficiency of two designed ASOs targeting Malat1 transcripts in GC-2 cells by performing fluorescence in situ hybridization (FISH) two days after infection." (PMID 34920761, 2021). "Studies on MALAT1 in inflammatory injury following lung transplant interestingly showed that the silencing of MALAT1 alleviated inflammatory injury by inhibiting neutrophil chemotaxis and immune cell infiltration to the site of infection." (PMID 33138195, 2020). "For example, both the transcription and infection by HIV-1 were shown to be increased by lnc-MALAT1." (PMID 32850817, 2020). "Among those, we show that suppression of Malat1 is a hallmark of CD4+ T cell activation, but its complete deletion results in more potent immune responses to infection." (PMID 32321759, 2020). "Contrastingly, HIV-1 replication is lower in MALAT1 KO Jurkat cells, and MALAT1 is thought to enhance infection by detaching EZH2 from binding the HIV-1 LTR promoter." (PMID 31336952, 2019). "We then knocked down MALAT1 expression in PHA-P-activated primary CD4+ T cells by infection with lentiviruses containing MALAT1 shRNA for 2 days, and then infected them with replication competent virus HIV-1/NL4-3 for additional 4 days." (PMID 30788509, 2019). "In this report, for the first time we show activation of Malat1 following infection by two flaviviruses, both of which activate the UPR in host cells." (PMID 26634309, 2015).
infection (continued). "MA10 infection induced six down-regulated (Pllp, Malat1, Myrf, Mag, Ptgds, Ugt8a) and two upregulated DEGs (Sgk1, Mbp), while Aβ pathology resulted in one down-regulated (Hmgb1) and ten up-regulated DEGs (Apoe, B2m, Clu, Cstd, Gfap, Psen1, Pllp, Cst7, Cd9, Plp1)." (PMID 41497643, 2025). "MALAT1 has been previously reported to promote HIV-1 transcription and infection, and MALAT1 influences gene expression by several mechanisms, including regulating the recruitment of specific chromatin modifiers such as the Polycomb Repressive Complex 2 (PRC2)." (PMID 40198713, 2025). "On the other hand, at 24 h post-infection, three splicing variants of the Ptgs2os2 gene (ENSMUST00000241778.1, ENSMUST00000245671.1, and ENSMUST00000241512.1), one of the Malat1 gene (ENSMUST00000249653.1), and one of the Gas5 gene (ENSMUST00000159037.3) were overexpressed in infected RAW264.7." (PMID 38464511, 2024). "Additionally, new research on HIV-1 has shown that MALAT1 regulates promoter-enhancer interactions to enhance viral transcription and infection." (PMID 38389521, 2024). "Hence, we used qPCR to evaluate the expression of lincRNA-Cox2, Lethe, lincRNA-EPS, Malat1, and Gas5 during the first 12 h of infection in RAW 264.7 cells." (PMID 38464511, 2024). "We observe that Malat1 exhibits a decrease in expression at 8 h post-infection, followed by an increase in the count of the same transcript at the 24 h post-infection, which could be related to the increase in the number of splicing variants observed." (PMID 38464511, 2024). "We anticipate that MALAT1 might also act as an agent for the regulation of infiltration to the site of infection." (PMID 35807375, 2022). "Interestingly, silencing MALAT1 alleviated inflammatory injury by inhibiting neutrophil chemotaxis and immune cell infiltration to the site of infection." (PMID 32646047, 2020). "Overall, our findings reveal Malat1 as a negative regulator of immunity to infection." (PMID 32321759, 2020). "The work presented in this study reveals one mechanism employed by Malat1 to shape immunity to infection and indicates that this lncRNA, like IL-10, plays a critical role in controlling the fragile equilibrium between effective pathogen clearance and enhanced immunopathology." (PMID 32321759, 2020). "The endogenous MALAT1 in HEK293T cells could be efficiently knocked out by infection with lentiviruses containing MALAT1 specific lentiCRISPR gRNAs (or off-target control)." (PMID 30788509, 2019). "In contrast, CYTOR, FOXD3-AS1, and MALAT1 were consistently downregulated during the infection." (PMID 31547203, 2019). "In addition, the LPS‐induced upregulation of MALAT1 was abolished by LV‐shMALAT1 infection." (PMID 39390627, 2024). "The impact of MALAT1 on the immune response to infections is complex and may be pathogen specific." (PMID 37079384, 2023). "However, the epigenetic response to HSV-2 is more complex than VP16-mediated upregulation of MALAT1, as infection led to other epigenetic changes including an increase in histone acetylations, including histones already modified with silencing marks such as H3K9me3." (PMID 37079384, 2023). "MALAT1 is known to negatively regulate the immune response and positively regulate the inflammatory response in the infected individuals, therefore downregulation of MALAT1 in the breakthrough infection suggests an upregulated immune response and downregulated inflammatory response." (PMID 36466827, 2022). "To evaluate the relationship between Malat1 and profibrogenic gene expression in infected mice treated with PZQ, we started treatment with PZQ at day 42 post-infection and isolated HSCs at day 56 for analysis of the profibrogenic genes." (PMID 39363237, 2024). "Knowing the global expression of lncRNA in B. abortus-infected BMM at 24 h, we proceeded to study the specific expression of five lncRNA: lincRNA-Cox2, lincRNA-EPS, Lethe, Malat1, and Gas5 in the RAW264.7 cell line at 8 and 24 h post-infection." (PMID 38464511, 2024).
infection (continued). "Our transcriptomic analysis shows that in response to infection, there are changes in the expression profile of lincRNA-Cox2, Lethe, lincRNA-EPS, Gas5 and Malat1." (PMID 38464511, 2024). "Our results demonstrate that infection of macrophages with Brucella abortus, induces significant changes in the expression of LincRNA-Cox2, Lethe, LincRNA-EPS, Gas5, and Malat1." (PMID 38464511, 2024). "Increased expression of NEAT1, MALAT1, EGOT, PVT1, MIAT has been also observed in infection with other viruses." (PMID 34940755, 2021). "The time-course of infection and the 72-h infection by HIV-1 significantly increased MALAT1 expression in all these CD4+ T-lymphocyte cell types." (PMID 30788509, 2019). "Taken together, we have identified the critical role of lncRNA MALAT1 in promoting HIV-1 transcription and infection at molecular levels." (PMID 30788509, 2019). "MALAT1, in conjunction with lncRNA NEAT1, has demonstrated potential as biomarkersfor HIV infection, following the identification of elevated amounts of these long non-coding RNAs in peripheral blood mononuclear cells(PBMCs) after infection." (PMID 41393400, 2025). "Considering the differences observed in the expression profile of the analyzed lncRNAs in B. abortus-infected RAW264.7 macrophages at 8 and 24 h post-infection, we examined the expression levels of lincRNA-Cox2, Lethe, lincRNA-EPS, GAS5, and Malat1 by RT-qPCR after 1, 6, and 12 h post-infection." (PMID 38464511, 2024). "Although some of the phenotypes observed with LCMV were attenuated or absent during acute infection with LM-GP33 at day 7, Malat1:miR-15/16 interaction had more pronounced effects on memory cell populations at later times post infection." (PMID 38127070, 2023). "MALAT1, along with lncRNA NEAT1, have been shown to be potential biomarkers for HIV infection, after the detection of high levels of both lncRNAs in peripheral blood mononuclear cells (PBMCs) upon infection." (PMID 32646047, 2020). "To confirm these findings, we used specific small interfering RNAs (siRNAs) to knockdown endogenous MALAT1 in HEK293T cells, and observed significantly diminished infection of a single-cycle infectious HIV-Luc/VSV-G virus, and significantly decreased expression of gag mRNA." (PMID 30788509, 2019). "Moreover, we found that MALAT1 promoted HIV-1 transcription and infection, as its knockdown by CRISPR/Cas9 markedly reduced the HIV-1 long terminal repeat (LTR)-driven gene transcription and viral replication." (PMID 30788509, 2019). "Although the abundance of some lncRNAs with immunomodulatory activity, such as lincRNA-EPS, Lethe, Malat1, and Gas5, does not change significantly at 24 h post-infection, lincRNA-Cox2 (Ptgs2os2) was highly overexpressed in these cells during the Brucella infection." (PMID 38464511, 2024). "The results showed that 1 and 6 h post-infection with S2308, RB51, or stimulation with HKBA did not significantly affect the expression of lincRNA-Cox2, Lethe, lincRNA-EPS, GAS5, and Malat1 in RAW264.7 macrophages compared to the unstimulated group." (PMID 38464511, 2024). "We have previously reported that a lack of MALAT1 results in lower levels of MAF and IL10 in mice and as a consequence, greater host resistance to infection or increased immunopathology." (PMID 36869729, 2023). "We observed that the levels of the nuclear, polyadenylated forms of MALAT1 or NEAT1 RNA did not increase dramatically but rather declined in abundance during lytic infection, after normalization to 18S rRNA levels." (PMID 22022268, 2011).
cardiovascular diseases (30 papers, 2014 to 2025). "Metastasis-associated lung adenocarcinoma transcript 1 (MALAT1) is a long non-coding RNA (lncRNA) that is considered to be associated with susceptibility to cardiovascular disease." (PMID 31024342, 2019). "Furthermore, the association of MALAT1 with miRNAs such as miR 155 5p, miR 142 3p, and miR 30e emphasizes its role in gene expression relevant to cardiovascular diseases." (PMID 39171328, 2024). "In recent years, association between lncRNA, MALAT1, and cardiovascular diseases are popular." (PMID 30833365, 2019). "The inhibition of MALAT1 holds therapeutic potential for the progression of salt-induced hypertension and cardiovascular disease (CVD)." (PMID 38791545, 2024). "Recently, several researchers found that aberrant expression of MALAT1 plays roles in cardiovascular disease." (PMID 31227612, 2019). "Moreover, MALAT1 is involved in angiogenesis and inflammation, where inflammation is associated with the occurrence of recurrent miscarriage, and recurrent miscarriage may increase the risk of cardiovascular disease." (PMID 31024342, 2019). "MALAT1 has also been reported to be involved in endothelial cell function and cardiovascular disease." (PMID 30150986, 2018). "Initially, MALAT1 was indicated in tumorigenesis, metastasis, and cardiovascular diseases." (PMID 40395673, 2025). "Malat1 has been extensively studied in cardiovascular diseases." (PMID 37022488, 2023). "MALAT1 plays a great role in cardiac remodeling and cardiovascular diseases." (PMID 34745428, 2021). "However, the role of MALAT1 in cardiovascular disease is understudied and reports suggest it may be beneficial against cellular apoptosis." (PMID 38132140, 2023). "Several lncRNA–mRNA regulatory axes are involved in the action mechanisms of MSC-Exos in cardiovascular diseases, such as KLF3-AS1/sirtuin 1 (SIRT1), MALAT1/autophagy-related 4a (ATG4a), urothelial cancer associated 1 (UCA1)-Bcl-2, and Mir9-3hg/Pum2." (PMID 38812041, 2024). "LncRNA MALAT1, which was firstly reported to participate in the progression of NSCLC and affect NSCLC cell metastasis, was recently revealed plays important role in in cardiovascular disease." (PMID 31227612, 2019).